INS (insulin)
Diseases named in the same sentence as INS in open-access papers (continued):
Sharing a sentence is not in itself a finding about the gene and the disease.
diabetes (continued). "Among subjects without diabetes, insulin and HOMA-IR were higher in subjects with PN compared with those without PN." (PMID 35651981, 2022). "Diabetes‐related increases in LDH activity may disrupt glucose metabolism and reduce insulin sensitivity." (PMID 36305681, 2022). "Diabetes is a chronic and progressive disease that occurs in the pancreas when it is no longer able to make a hormone known as insulin or when the body is unable to use it properly." (PMID 36428864, 2022). "Among the 3,067 enrolled participants, 307 participants with diabetes, 4 with missing fasting glucose, fasting insulin or triglyceride, and 37 without CTA or MRI examinations were excluded, and a total of 2,719 participants were available for final analysis." (PMID 36221073, 2022). "Diabetes is a long-term but controllable disease that happens when the pancreas does not make enough insulin or when the body does not use the insulin it makes." (PMID 36140666, 2022). "Consistently, it was found that proteasomal degradation of p300 contributes to beta cell apoptosis in diabetes condition, while removal of Set7/9 methyltransferase and disturbance of active H3K4 histone mark in beta cells reduces Pdx1 expression and insulin secretion." (PMID 36246880, 2022). "The definition of the ISF in represents the sensitivity to the injected exogenous insulin, which is of interest to diabetes practitioners, and not the sensitivity to the blood plasma insulin concentration which is quite common in current studies." (PMID 35577814, 2022). "Type 2 diabetes mellitus (T2DM) is a chronic metabolic disease, which is characterized by hyperglycemia, chronic insulin resistance, progressive decline in β-cell function, and defect in insulin secretion." (PMID 36232291, 2022). "The marked reduction in time spent with glucose >250 mg/dL in the subgroup with baseline HbA1c values ≥10% was achieved without significant differences in diabetes medication changes between groups, including the initiation of prandial insulin." (PMID 34962151, 2022). "Diabetes mellitus (DM) is a chronic, endocrine, metabolic disease characterized by an impaired capacity to utilize plasma glucose, secondary to the lack of insulin secretion, or provoked insulin balance." (PMID 36407145, 2022). "Type 2 diabetes mellitus (T2DM) is a heterogeneous metabolic disease characterized by impaired pancreatic beta cell insulin secretion, increased hepatic glucose uptake, and insulin resistance in peripheral tissues such as the liver, skeletal muscle, and adipose tissue." (PMID 36355489, 2022). "On the other hand, the use of insulin to reduce blood glucose levels is limited to patients with advanced diabetes, and no regimens have been reported to improve patient outcomes." (PMID 35268317, 2022). "Fasting insulin was lower in nondiabetic women than men, and this was not seen in individuals with diabetes." (PMID 34657182, 2022). "Diabetes is a chronic disease that occurs either when the pancreas does not produce enough of the blood sugar-regulating hormone insulin or when the body cannot effectively use the insulin it produces." (PMID 35267955, 2022). "On the other hand, the results derived from standard linear regression, from regression stratified by SB levels, from ISM and from compositional approaches are in disagreement for fasting glucose, 2-h glucose, 2-h insulin, insulin sensitivity, HOMA-IR, incident diabetes, CRP and IL-6." (PMID 35544519, 2022). "Model 3 was additionally modified for diabetes-related factors, including diabetes duration, use of glucose-lowering medications (none, insulin, oral hypoglycemic agent, or others), history of CVD or hypertension, HbA1c level, TC level, HDL-C level, and eGFR." (PMID 36419168, 2022). "Female rats become obese but do not develop diabetes, maintaining good insulin sensitivity for a prolonged time." (PMID 35782067, 2022).
diabetes (continued). "In order to further investigate the effect of TET2 on the upregulation of the Txnip in diabetic mice DRG neurons, we used HG (25 mM glucose without insulin) to culture DRG cells to mimic diabetes in vitro." (PMID 36527131, 2022). "Further, our stratified analysis according diabetes duration and sensitivity analysis in which concomitant insulin use was not allowed provided additional support for the notion that our observed associations were due to SGLT-2i use." (PMID 35894858, 2022). "Selective SGLT-2 inhibitors, such as empagliflozin, dapagliflozin or canagliflozin, used in the treatment of diabetes, have a unique mechanism of action independent of both the effect on insulin production and the effect on insulin sensitivity." (PMID 36497303, 2022). "Early diabetes therapies, such as the sulfonylureas, targeted hyperglycemia by directly stimulating insulin release independent of glucose." (PMID 35204835, 2022). "After eating, blood sugar levels increase, and for those without diabetes, the pancreas increases insulin release into the blood." (PMID 35224106, 2022). "Diabetes mellitus (DM) is a chronic disease that occurs when the pancreas is no longer able to produce insulin, or when the body cannot effectively use insulin, which causes an increase in blood glucose levels." (PMID 35684376, 2022). "Known as non-insulin-dependent diabetes mellitus, T2DM is largely induced by insulin resistance and dysfunction of insulin-producing β cells, which decreases the tissue sensitivity to insulin and has insufficient biological effects, thereby leading to hyperglycemia." (PMID 36438731, 2022). "Type 1 diabetes mellitus (T1DM) is a condition in which the body is no longer able to produce adequate amounts of insulin as a result of the destruction of pancreatic beta cells, most often due to autoimmune cause, leading to increased blood glucose levels." (PMID 36176818, 2022). "Moreover, ER stress reduces insulin signaling during the development of diabetes via activation of JNK, plus it induces pancreatic apoptosis, which worsens diabetes complications." (PMID 36618403, 2022). "Patients with younger age, shorter duration of T2DM, lower preoperative HbA1c and FBS, higher BMI, who were not on insulin therapy, and not having a family history of obesity were the best candidates to achieve a prolonged diabetes remission." (PMID 36289529, 2022). "This can be related to the fact that in the study conducted on rats with alloxan-induced diabetes, the authors noted that insulin production in the pancreas was not elevated after silymarin treatment." (PMID 35406062, 2022). "Taking into account the degrees of macrophage infiltration (maximum approximately 8 weeks of diabetes then dropping), the effects of RAGE inhibition on insulin sensitivity may be attenuated after 8 weeks of diabetes." (PMID 36477360, 2022). "This study showed that previous GDM was associated with significantly higher risk of all cardiovascular and metabolic outcomes and that the association was exacerbated by insulin treatment in GDM pregnancy in women with and without subsequent diabetes." (PMID 36085031, 2022). "A perioperative hypoglycemic risk prediction model was developed that was mainly composed of four predictors: duration of diabetes ≥ 10 year, body mass index (BMI) < 18.5 kg/m2, standard deviation of blood glucose (SDBG) ≥ 3.0 mmol/L, and preoperative hypoglycemic regimen of insulin subcutaneous." (PMID 35538461, 2022). "At the same time, the incidence was found to be 20% in type 2 diabetes patients taking treatment with insulin or without insulin with less than five years of progression of diabetes." (PMID 36475134, 2022). "Preexisting diabetes was present in 54 (4%) patients without insulin, 157 (24%) patients with bolus-only insulin, 216 (78%) patients with basal-bolus insulin, and 84 (69%) patients with premixed insulin." (PMID 34986826, 2022).
diabetes (continued). "Putting a patient on insulin, for some doctors, indicates that he has failed to control his diabetes with oral medications and now needs to force him into a difficult treatment regime." (PMID 35854336, 2022). "In people without diabetes, when glucose levels fall pancreatic ß‐cell insulin production is decreased and α‐cell glucagon secretion increased providing a stimulus to increase hepatic glucose production." (PMID 36251572, 2022). "There were no reports of type 2 diabetes or pre‐diabetes in the cohort but fasting insulin and fasting glucose measurements were not part of the standard clinical work up." (PMID 35281659, 2022). "Other factors include the long duration of diabetes, combined oral antidiabetic and insulin therapy, noncompliance to medication, poor dietary regimen, and physical inactivity." (PMID 36415391, 2022). "In the Diabetes Control and Complications Trial (DCCT), patients who received the conventional therapy for 6.5 years were compared to the group of patients who received the intensive insulin therapy." (PMID 34991585, 2022). "Although their analysis incorporated a binary classification of T2D duration, it did not include other patient characteristics, such as insulin use, diabetes medication use, and glycemic control, that differentiate T2D response to bariatric surgery." (PMID 35157054, 2022). "In this case, the proband had an early-onset diabetes, no history of neonatal hypoglycemia, no history of ketosis, negative insulin-related antibodies, and no obvious insulin resistance." (PMID 36181023, 2022). "According to a study conducted in those without diabetes, insulin secretion is suppressed under hyperglycemic conditions, which contributes to the thickening of the lens and an anterior shift of the anterior pole; worsening the myopia." (PMID 35333875, 2022). "In nondiabetic patients, statin use was associated with significant increases in insulin level, fasting blood glucose and HOMA-IR, whereas no significant increase was observed in diabetes." (PMID 35627914, 2022). "There was no patient of LADA who was prescribed insulin treatment, while 10% of T2D patients were in insulin treatment with good glycaemic control during the course of diabetes management." (PMID 35804315, 2022). "In the case of diabetes, lack of insulin promotes metabolism to ketone body production, which can cause diabetic ketoacidosis." (PMID 35308269, 2022). "Diabetes is a chronic metabolic disease characterized by lack of insulin in the body leading to failure of blood glucose regulation." (PMID 35328783, 2022). "Type 2 Diabetes Mellitus (T2DM), the most prevalent metabolic disease, is characterized majorly by a combination of two major factors:impaired insulin production by pancreatic -cells and a failure of insulin-sensitive tissues to respond adequately to insulin." (PMID 37693079, 2022). "This study explores nutrition intervention for diabetes management via the improvement of insulin sensitivity without weight gain or adverse side effects." (PMID 36145160, 2022). "These patients were managed with one or more diabetes medications, including insulin, metformin, sulfonylureas and acarbose, or without any medications." (PMID 34585841, 2022). "Although patients with diabetes from different areas have somewhat different pathophysiological features, such as not being so obese or less insulin resistant, the role of insulin resistance in determining fracture risk is still under debate." (PMID 36120431, 2022). "Patients with nocturnal hypoglycemia level 2 presented longer diabetes duration, lower C peptide, and higher insulin dose than those without hypoglycemia and those with hypoglycemia level 1 (P < 0.05)." (PMID 36237834, 2022). "Although 95% of adults with diabetes have T2DM, we recognize that individuals younger than 30 years, especially those being treated with insulin, may have Type 1 Diabetes." (PMID 35465388, 2022).
diabetes (continued). "Also, we find that insulin use in theDCM group is lower than in the NDCM group, which indicate that partially reasonof DCM in diabetes was related with insulin use." (PMID 39076230, 2022). "Diabetes mellitus is a chronic disease characterized by abnormal glucose, protein, and lipid metabolism due to a lack of or reduced insulin action." (PMID 35625813, 2022). "Diabetes mellitus is a group of chronic metabolic diseases resulting from a relative or complete lack of insulin secretion by β-cells of the pancreas, and/or the decreased response to insulin by target tissues." (PMID 36235503, 2022). "Both hepatic and peripheral insulin sensitivity, as well as levels of hepatic glycogen, were additionally analysed in volunteers who only used metformin as diabetes treatment (n=7) and this did not alter the outcomes." (PMID 35871650, 2022). "Exogenous insulin is the only treatment for patients to control hyperglycemia and control disease, so it is also known as insulin-dependent diabetes mellitus (IDDM) in the first worldwide accepted classification of diabetes." (PMID 35966750, 2022). "This enhanced delineation was possible without biochemical measures of insulin secretion and resistance or diabetes autoantibody data." (PMID 35587468, 2022). "The mechanisms for the increase in TGS1 levels in models of diabetes are not completely identified, but we show that insulin in a paracrine fashion is involved." (PMID 35041827, 2022). "In Japanese patients, MODY6 individuals developed diabetes at less than 15 years of age, as well as diabetic ketoacidosis with a defect of early-phase insulin secretion without insulin dependence, unlike for Europeans." (PMID 36361703, 2022). "The glucose concentration of the lens in a diabetes environment does not depend on insulin, and glucose in the lens is reduced to sorbitol, which is difficult to convert into fructose." (PMID 35406761, 2022). "Diabetes is characterised by hyperglycemia, or high blood glucose, which results from a lack of insulin or from cells' insensitivity to insulin." (PMID 36348847, 2022). "Despite the increased insulin resistance, no pig in our study developed overt diabetes, perhaps because we did not observe the animals until older age or because pancreatic β-cells have a greater capacity to increase insulin secretion." (PMID 36290436, 2022). "Soft drinks ranked as the 8th and 6th most consumed food subcategory of participants with T2D not taking insulin and those without diabetes, and contributed 5th and 2nd most to energy, respectively." (PMID 36014790, 2022). "The medications, including hypoglycemic and nonhypoglycemic drugs, insulin dosage, comorbidities, diabetes-related complications, treatment strategies, and annual medical costs, were recorded." (PMID 36093107, 2022). "Subjects with DR were more often male and daily insulin users, had a longer duration of diabetes, and lower body mass index than those without this complication." (PMID 35659624, 2022). "Insulin was started in 35% of this cohort as a new treatment during admission, and in this group, 82% were already on oral medication for diabetes before their admission, compared to 62% who did not need insulin." (PMID 35256883, 2022). "In this study, we developed and tested an algorithm for identifying individuals with AD, specifically an insulin-sufficient non-metabolic diabetes phenotype, in a large EHR database as a potential recruitment strategy for the RADIANT study." (PMID 36508462, 2022). "Nevertheless, patients in the high BF group had higher levels of HbA1c, pointing to a possible early alteration in glucose homeostasis and insulin resistance due to the increase in body fat, regardless of the low rate of diabetes mellitus diagnosis." (PMID 35208476, 2022). "Diabetes is a chronic non-communicable disease that occurs when the pancreas can no longer produce insulin, or when the body can no longer use insulin." (PMID 36175969, 2022).
diabetes (continued). "Patients with diabetes have lower magnesium levels compared to control patients, as IGF1 is able to increase intracellular magnesium levels and also to reverse the dull response of hypertensive cells to insulin." (PMID 35395053, 2022). "The clinical diagnosis of MODY is based on young onset (before the age of 25), presence of diabetes in at least 3 consecutive generations, absence of β-cell autoantibodies, and relatively preserved endogenous insulin secretion, according to some studies." (PMID 35029855, 2022). "Some guidelines allow for the use of either insulin or noninsulin antidiabetic agents for gestational diabetes, but only insulin is recommended for pregnant women with preexisting type 2 diabetes mellitus (T2DM)." (PMID 34953068, 2022). "From 1988-1994 to 2013-2020, the proportion of patients with diabetes who received insulin and achieved glycemic control did not significantly change, from 29.2% (95% CI, 22.6%-36.8%) to 27.5% (95% CI, 21.7%-34.2%)." (PMID 36538330, 2022). "Diabetes is a metabolic disorder in which the blood glucose level is increased because of a lack of insulin production or a reduction in insulin sensitivity and function." (PMID 35527404, 2022). "Diabetes mellitus (DM) encompasses several heterogeneous disorders that occur when a lack of insulin or insulin resistance evokes a high level of blood glucose." (PMID 35979435, 2022). "Diabetes mellitus is a chronic disease characterized by abnormal glucose, protein, and lipid metabolism due to a lack of or decreased insulin activity." (PMID 35625813, 2022). "When healthy rats were exposed chronically to a high AGE diet, insulin secretory defects and islet infiltration in the absence of diabetes were observed." (PMID 36359899, 2022). "Pre-diabetes is characterised as a combination of impaired glucose tolerance (IGT) and impaired fasting glucose (IFG) which can be attributed to moderate insulin resistance in insulin-dependent tissues." (PMID 35898447, 2022). "The efficacy of receptor agonists is also different in animals with and without diabetes as levels of insulin and blood glucose can affect the pathophysiology and outcomes of stroke." (PMID 35370875, 2022). "In patients without diabetes, antecedent bouts of hypoglycemia, induced by either exercise or pharmacologically administered insulin, have been shown to blunt or reduce the neuroendocrine and glucoregulatory responses to subsequent bouts of exercise." (PMID 36083870, 2022). "In total, 75% of obese patients do not develop diabetes due to the effect of compensatory insulin secretion; maintenance of functional pancreatic β-cells is thought to be the ultimate result of diabetes treatment." (PMID 35625786, 2022). "Malondialdehyde turned out to be higher in patients with diabetes mellitus type 2 that was not treated with insulin or metformin than in those treated with both medications (p = 0.052)." (PMID 35742776, 2022). "Diabetes is mainly classified into type 1 diabetes mellitus (T1DM), which is caused by absolute lack of insulin secretion, or type 2 diabetes mellitus (T2DM), which is mostly caused by insulin resistance in peripheral organs such as the liver muscle, and fat." (PMID 35966093, 2022). "According to the degree of insulin dependence, diabetes can be divided into insulin- and non-insulin-dependent diabetes mellitus also called type 1 diabetes mellitus (T1DM) and type 2 diabetes mellitus (T2DM)." (PMID 36479195, 2022). "Diabetes mellitus is a chronic noncommunicable disease in which the body cannot produce or properly use insulin, a hormone that regulates the amount of glucose in the blood." (PMID 36177396, 2022). "Oxidative and dicarbonyl stress, driven by excess accumulation of glycolytic intermediates in cells that are highly permeable to glucose in the absence of effective insulin activity, appear to be the chief mediators of the complications of diabetes." (PMID 36135209, 2022).